SNORA41 (small nucleolar RNA, H/ACA box 41)
Synonyms: ACA41; SNORA41A
Gene: Small nucleolar RNA gene on chromosome 2 (206,162,228 to 206,162,359, forward strand). Ensembl gene ENSG00000207406.
Gene Ontology:
Biological process: RNA processing
Cellular component: nucleolus
Homologues: Orthologues: chimpanzee SNORA41 (99% identical), macaque SNORA41 (97% identical), rabbit SNORA41 (94% identical), pig SNORA41 (89% identical), rat Snora41 (89% identical), mouse Gm23723 (88% identical), mouse Snora41 (87% identical), guinea pig SNORA41 (83% identical). Paralogues in human: SNORA41B (85% identical).
Diseases named in the same sentence as SNORA41 in open-access papers:
SNORA41 is named in the same sentence as 2 diseases in open-access papers, as found by Europe PMC text mining. Sharing a sentence is not in itself a finding about the gene and the disease. The quoted sentences say what the papers report.
cancer (2 papers, 2017 to 2021). A tumor composed of atypical neoplastic, often pleomorphic cells that invade other tissues. "The interactions of downregulated GRHL3 in the control offspring with downregulated GPCPD1 and SNORA41 are indicative of good cancer prognosis." (PMID 28673325, 2017). "In contrast, the ten node genes in the mammary glands of the offspring of dams fed the CON diet were linked to changes in the expression of genes indicative of reduced cancer risk (downregulation of DPF3, SNORA41) and improved immune functions (upregulation of ZBP1, ZFP683; downregulation of EGR3)." (PMID 28673325, 2017).
SNORA41 also shares sentences with these, for which no sentence is quoted: non-small cell lung carcinoma (1 paper).